RHO (rhodopsin)
Diseases named in the same sentence as RHO in open-access papers (continued):
Sharing a sentence is not in itself a finding about the gene and the disease.
retinal degeneration (continued). "Mutations in genes such as RHO (Rhodopsin), RP1, and RPGR (retinitis pigmentosa GTPase regulator) have been among the most described, leading to a disruption in key photoreceptor functions with subsequent retinal degeneration." (PMID 40731809, 2025). "In addition, the removal of excess rhodopsin through ubiquitination can serve as a protective mechanism against light-induced retinal damage, and retinal degeneration in mice can be delayed by increasing photoreceptor proteasomal activity." (PMID 41316449, 2025). "Interestingly, rhodopsin mislocalisation is reported in IFT88/Tg737 mutant mice and mutations in IFT88 have been found in individuals with non-syndromic recessive retinal degeneration." (PMID 39934925, 2025). "Characterization of the PROTEOSTAT staining in those mice demonstrated that neither retinal degeneration nor rhodopsin mislocalization by themselves causes aggregation of rhodopsin or any other protein that are detectable by PROTEOSTAT." (PMID 39875362, 2025). "Thus, we assessed photopic signals at late-stage retinal degeneration in the RHO P23H mice to investigate cone neuron–specific function." (PMID 40215317, 2025). "Retinal degeneration required rhodopsin expression since photoreceptor cell loss is not evident at an age where rhodopsin expression is minimal." (PMID 39875362, 2025). "Studies in animal models expressing P23H rhodopsin suggest that there may be alternate mechanisms leading to retinal degeneration besides those related to the mislocalization and aggregation of the mutant receptor." (PMID 38365903, 2024). "During retinal degeneration these pathways were found activated, as shown by the progressive increased expression of CHOP and decreased expression of BIP in photoreceptors with a misfolding mutation in RHO." (PMID 38370034, 2024). "Rhodopsin transcript levels were reduced even when normalized to that of transducin, indicating that once a significant level of retinal degeneration occurs, transcription may become affected." (PMID 38365903, 2024). "Upon delivery to mice by intraperitoneal injection, PR3 has been found to be safe and effective in mitigating retinal degeneration, and improving visual function in the P23H rhodopsin mouse model, suggesting photoregulins are attractive preclinical candidates to treat humans with RHO-related adRP." (PMID 38661530, 2024). "Control studies in Prph2Rd2 mice demonstrate that retinal degeneration does not cause mislocalized WT rhodopsin to form a species, such as an aggregate, that can be stained by PROTEOSTAT." (PMID 38365903, 2024). "The RHO variant (p.Glu150Lys) identified in current study lies in the cytoplasmic domain of Rhodopsin that affects its signaling activity as a G-protein-coupled receptor and consequential aberrant trafficking as well as initiation of retinal degeneration usually lead to RP." (PMID 37165311, 2023). "We previously performed single-cell RNA sequencing (SC RNA-Seq) analysis on retinas from adult WT and P23H transgenic zebrafish (expressing Flag-tagged P23H mutant rhodopsin in rods) to examine how the retinal environment changed during retinal degeneration and regeneration." (PMID 38322239, 2023). "Lacking a progressive phenotype, the restoration of the USH2 protein complex at the periciliary region, and normal rhodopsin trafficking, provide valuable biomarkers to evaluate future therapeutic strategies for ADGRV1-associated retinal degeneration in the adgrv1rmc22 zebrafish." (PMID 37371069, 2023). "The protein partners identified in our study may provide new insights into how photoreceptors recognize and clear mutant rhodopsin, offering possible novel targets involved in retinal degeneration pathogenesis." (PMID 36258031, 2022). "Although it was previously reported that the RHO‐P347S mutation causes mis‐trafficking of RHO proteins, the pathogenic mechanisms underlying the retinal degeneration, as well as the final cell death mechanisms, are not fully elucidated in this model." (PMID 36194668, 2022).
retinal degeneration (continued). "Taken together, these results imply that M-Pn is clathrin-dependently internalized as a result of its interaction with arrestin 2 and that hyperphosphorylation in the rdgC and norpA mutants is etiological for retinal degeneration due to long-lived arrestin–rhodopsin complexes." (PMID 36499010, 2022). "Our study provides the first proteomic analysis of wild-type and mutant rhodopsin protein interaction partners isolated from native retina, and these datasets provide a resource for further investigation of rhodopsin in rod health and retinal degeneration." (PMID 36258031, 2022). "It remains to be examined whether mammalian CRAPBs similarly regulate rhodopsin levels and affect retinal degeneration." (PMID 34714826, 2021). "Cellular mechanisms that regulate Rhodopsin protein levels affect retinal degeneration." (PMID 34714826, 2021). "To determine whether this horizontal cell phenotype is a consequence of retinal degeneration, we examined this phenotype in mice with photoreceptor-specific inactivation of the BBSome induced by Cre recombinase driven by the rhodopsin promoter." (PMID 32433491, 2020). "Furthermore, knocking out the Emc3 gene in mammalian rod photoreceptor cells led to dysregulated rhodopsin trafficking and retinal degeneration, as seen in flies, suggesting that EMC function is conserved in mammals." (PMID 31263175, 2020). "The delocalization of rhodopsin and stunted outer segments observed in the P23H transgenic zebrafish is consistent with characteristics of rod photoreceptors in models of RP that show retinal degeneration." (PMID 33036185, 2020). "ERdj5 facilitates degradation of misfolded proteins via ERAD; therefore, ablation of Erdj5 could exacerbate retinal degeneration in P23H rhodopsin mouse models." (PMID 32196553, 2020). "However, recent reports argue against a complementary function of autophagy in degrading misfolded rhodopsin–inhibiting autophagy reduced retinal degeneration in RhoP23H mice by promoting proteasomal degradation of misfolded mutant rhodopsin." (PMID 33137101, 2020). "Without these chaperons the rhodopsin protein fails to properly mature, leading to retinal degeneration, as seen with mutations in rhodopsin itself." (PMID 31263175, 2020). "Interestingly, at an early age, Vps34 KO rods have been shown to display normal structure and function and rhodopsin trafficking, but by 12 weeks, the rods undergo a progressive retinal degeneration." (PMID 33171845, 2020). "Other forms of mutated rhodopsin (T4K, T4N, and T17M) show a lack of glycosylation of the residue N15, which leads to light-dependent retinal degeneration." (PMID 32435178, 2020). "It has been reported that knockdown of Psd resulted in light-dependent retinal degeneration by preventing autophagy-dependent rhodopsin degradation since the abundance of PE could positively regulate autophagy." (PMID 33064773, 2020). "Thus, too low or too high levels of exogenous rhodopsin can lead to cell toxicity and retinal degeneration." (PMID 31126147, 2019). "Interestingly, knocking down the proapoptotic partner of CHOP, ATF4 in a T17M rhodopsin mutant mouse model resulted in decreased retinal degeneration and improved PR survival." (PMID 31344897, 2019). "We hypothesize that, as a consequence of CME disturbance in the retina, rhodopsin accumulates in the photoreceptors, leading to cell death and retinal degeneration." (PMID 31117272, 2019). "Retinal degeneration in crb mutants is a consequence of light exposure and is rescued in the absence of vitamin A, a precursor to the chromophore retinal, which is in turn a component of the light-activatable photopigment rhodopsin." (PMID 31834921, 2019). "As an alternative to intravitreal injections, Nec-1s was delivered through subcutaneous delivery and rescued ONL thinning in a mouse P23H rhodopsin model of retinal degeneration, suggesting that Nec-1s can have an effect in the retina through systemic and non-local delivery." (PMID 31779177, 2019).
retinal degeneration (continued). "Unlike rod and cone opsins, missense mutations in melanopsin are unlikely to give rise to deleterious consequences, such as retinal degeneration and congenital stationary night blindness, which are associated with missense variants in rhodopsin." (PMID 29718372, 2018). "In the present study, we attempted to characterize the SD-OCT findings of retinal degeneration in transgenic rhodopsin S334ter rats (line 4), a typical Class 1 mutant, to seek any particular characteristics in the OCT findings in relation to the morphological and electrophysiological features." (PMID 30581855, 2018). "Rhodopsin S334ter transgenic rats (line 4) were employed as a model of retinal degeneration." (PMID 30581855, 2018). "One consists on the "non-blue" (above 500 nm) wavelengths that excite rhodopsin and generate toxic waste, but do not cause retinal degeneration." (PMID 29543853, 2018). "Therefore, the role of ER stress in the pathogenesis of rhodopsin retinal degeneration is unresolved." (PMID 29036441, 2017). "This could explain why T17M rhodopsin mice with inherited retinal degeneration experience a preservation of retinal function and photoreceptor cell death when their retina is deficient in TNFa, a downstream ATF4 target." (PMID 29326555, 2017). "It has been proposed that mislocalized rhodopsin contributes to photoreceptor cell death, that the level of mislocalized rhodopsin most likely correlates to the speed of retinal degeneration and that the reduction of mislocalized rhodopsin can ameliorate rod cell death." (PMID 29203866, 2017). "Additionally, overexpression of BiP reduced ER stress and protected against retinal degeneration in a P23H rat model, and ER stress was also observed in hT17M rhodopsin mice." (PMID 29036441, 2017). "Metformin treatment did not affect photoreceptor function or survival, confirming that the adverse effects of metformin in the P23H-1 rat model and P23H KI mouse model are specific to rhodopsin and not a general feature associated with retinal degeneration." (PMID 28065882, 2017). "Therefore, fluorescence of Rh1::GFP is a good marker for rhodopsin levels and is suitable for use in screens targeting mutants of retinal degeneration." (PMID 26659849, 2015). "Ablation of CHOP, selective activation of ATF6 or PERK, disruption of CDK5 and MEKK1 pathway, or the stimulation of ERAD may serve as a powerful therapeutic strategy against rhodopsin mutants induced RP and reverse severe retinal degeneration." (PMID 25530840, 2014). "In addition to the issue of retinal degeneration (i.e. photoreceptor cell loss), of particular interest is the role of RDS and rhodopsin (primary components of the disc rim and lamellae, respectively) in OS morphogenesis." (PMID 24897172, 2014). "Further study showed that endoplasmic reticulum (ER) stress response is involved in retinal degeneration in T17M rhodopsin retinas in vivo, accompanied by the up-regulation of autophagy markers and the activation of mitochondrial apoptosis via the up-regulation of pro-apoptotic Bcl2." (PMID 25530840, 2014). "Since Chop has been shown to regulate the expression of rhodopsin through a microRNA, miR-708, in 293T cells, deleting Chop could alter rhodopsin levels in photoreceptors and potentially influence retinal degeneration." (PMID 24523853, 2014). "However, disrupted RHO trafficking and an increase in peIF2α are the hallmarks of accelerated retinal degeneration." (PMID 24068865, 2013). "In fact, caspase-3 activation is generally seen in animal models with either inherited or induced photoreceptor degeneration: the rd-1 mouse, rhodopsin mutant rat, chemically induced retinal degeneration, and photoreceptor degeneration following blue light exposure." (PMID 23922490, 2013). "We have also discovered that the increase in the rate of retinal degeneration in ADRP mice was not linked to the over-expression of RHO as expected but was instead associated with transcriptional repression in the T17M RHO retina." (PMID 23646198, 2013).
retinal degeneration (continued). "Therefore, we further proceeded to compare the T17M RHO and T17M RHO CHOP−/− retinas and search for the cellular signaling mechanism responsible for the severe retinal degeneration observed in T17M RHO CHOP−/− mice." (PMID 23646198, 2013). "Mislocalization of rhodopsin can occur as a secondary phenomenon to retinal degeneration." (PMID 23351594, 2012). "Also, mice with a targeted deletion of Ahi1 develop retinal degeneration with an accumulation of rhodopsin in the photoreceptor inner segments, possibly due to a decrease in the levels of photoreceptor Rab8 expression." (PMID 23351793, 2012). "Mice with 3 wild type genes and the P23H transgene might be expected to display an ongoing retinal degeneration, instead of a plateau, as shown for mice with 4 wild type rhodopsin genes." (PMID 23185477, 2012). "Activated rhodopsin is degraded in endosomal pathways in normal photoreceptor cells in Drosophila, and accumulation of activated rhodopsin in some Drosophila mutants leads to retinal degeneration." (PMID 22567011, 2012). "Dominant rhodopsin mutants showed progressive age-dependent and light-independent loss of the deep pseudopupil, without any apparent retinal degeneration at the morphological level." (PMID 22194648, 2011). "In a more recent screen, dominant neither inactivation nor afterpotential E (ninaE) alleles that undergo retinal degeneration have been isolated, some of which correspond to mutations in the same residues of human rhodopsin associated with ADRP." (PMID 22194648, 2011). "Quantification of the rhodopsin present in such mutant flies, especially for rhodopsin mutants, is a widely used assay in all studies, but the lack of any detailed insight into the fate of rhodopsin has led to questioning how low levels of rhodopsin lead to rhodopsin-mediated retinal degeneration." (PMID 22194648, 2011). "If the rhodopsin/Arr1 complex contributed to the severe retinal degeneration in the light-exposed transgenic Q344terrho+/− background, we would expect an amelioration of the retinal morphology in the light-exposed transgenic retinas when Q344ter is expressed in the RK−/−, Trα−/− genetic background." (PMID 20532191, 2010). "We addressed these questions by 1) breeding the Q344ter-expressing mice into the endogenous rhodopsin (rho)+/− and rho−/− backgrounds and 2) assessing the extent of retinal degeneration in dark-reared Q344ter mice and comparing this to the effect of controlled light-exposure to retinal degeneration." (PMID 20532191, 2010). "Finally, we plan to examine the zinc staining of the Rho and RPE65 KO animals and the efficacy of pyruvate and nicotinamide against rhodopsin RP mutant models of retinal degeneration." (PMID 21179242, 2010). "High levels of retinal docosahexaenoic acid do not protect mice expressing the VPP rhodopsin mutation from retinal degeneration." (PMID 20806040, 2010). "Substantiating this property may provide an important first step towards discovering the mechanism(s) that leads to the observed light-accelerated retinal degeneration in our transgenic Q344ter mouse model as well as other Class I rhodopsin mutants." (PMID 20532191, 2010). "We next asked, whether PKD-mediated retinal degeneration was light and age dependent, which is typical for defects in rhodopsin maturation or trafficking." (PMID 17592635, 2007). "Retinitis pigmentosa (RP) linked to RHO (which encodes rhodopsin) is the most frequent form of inherited retinal degeneration that leads to blindness, for which there are no current therapies." (PMID 18034880, 2007). "At PN28, the rhodopsin signal was extremely low, reflecting the advanced and nearly complete degeneration of rods in rd1 retinas at this time point, paralleling the well-established time course of the rd1 retinal degeneration." (PMID 17563719, 2007). "Overall, the retinal degeneration seemed not to be caused primarily by interference with rhodopsin trafficking." (PMID 17592635, 2007).